IL15 (interleukin 15)
Diseases named in the same sentence as IL15 in open-access papers (continued):
Sharing a sentence is not in itself a finding about the gene and the disease.
tumor (continued). "Three days following initial vvDD-IL15/Rα infection, IL-15/IL-15Rα levels rose to a detectable mean concentration of 2,581 pg/ml per 500 mg of tumor tissue by ELISA, while concentrations in tumors of PBS and vvDD treated mice were undetectable." (PMID 33679747, 2021). "Within the tumor microenvironment, IL-15 has been shown to maintain NK cell homeostasis and promote T cell proliferation." (PMID 33290281, 2021). "Immune factor including IFN-γ, granzyme B and IL-15 in both tumor tissues and (or) serum were also elevated." (PMID 34593005, 2021). "Ex vivo pre-culture with IL-15 resulted in the generation of anti-tumor CD8+ T cells with the central memory phenotype." (PMID 33671252, 2021). "Due to its impact on the immune system, the IL-15/IL-15α axis modulates the carcinogenesis process by inhibiting tumor growth." (PMID 33916844, 2021). "The combination of IL-12, IL-15 and IL-18 induces a memory-like NK cell which is long-lived and has enhanced anti-tumour effects." (PMID 34888493, 2021). "Overall, the anti-tumor efficacy of IL-15-based therapies depends on changes in the cellular and cytokine landscape within the tumor." (PMID 33671252, 2021). "These cells once activated with IL-15, demonstrated a higher cytotoxicity against K562 (≥ 90%; P ≤ 0.001) and SKOV3 tumor cells (≥ 65%; P ≤ 0.001) compared to IL-15/Hsp70-activated NK cells." (PMID 34098947, 2021). "A recent in vivo study has shown that an IL15-enhanced DC vaccine is a potent delayer of tumour growth, improves mouse survival, and induces a stronger Th1-skewed T-cell response." (PMID 33391542, 2021). "Multiple ways have been described that support a favourable differentiation profile; Expanding T cells in presence of IL-15, which supports a more central memory-like phenotype, also promotes anti-tumour immunity." (PMID 34421914, 2021). "Given widespread interest in IL-15 as a mediator of anti-tumor immunity in preclinical studies, numerous biological agents have been synthesized to mimic or inhibit the activity of IL-15 on target cells." (PMID 34681751, 2021). "Here the authors show that m6A-methyltransferase METTL3 deletion in NK cells leads to reduced function and protection against tumour challenge through suppressing response to IL-15." (PMID 34535671, 2021). "Although our results agree with the inhibition of inflammation through the increase in NFĸBIA we also observed an increase of interleukin-15, which is important in long-term immunosurveillance against tumours." (PMID 34449674, 2021). "IL-15/IL-15Rα complex has poor stability and can bind to IL-15Rβγ to decrease tumor immune efficacy." (PMID 34386015, 2021). "Nevertheless, elevated serum concentrations of IL-15 significantly correlate to those patients with a Grade 3 tumor." (PMID 32929618, 2021). "Cytokine activation, particularly by myeloid cell-derived IL15, can induce potent NK anti-tumor responses." (PMID 33708215, 2021). "The cytotoxic capacity of the NK cells treated with IL-15 and IL-15/Hsp70 against SKOV3 tumor cells was also assessed as a solid tumor model." (PMID 34098947, 2021). "In one such study, tumor-harboring mice with NK-92 cells or primary NK cells transduced with retroviral vectors producing IL-2 or IL-15 had increased proliferation and persistence." (PMID 34970253, 2021). "Vaccination with a BacMam-based IL-15:IL-15Rα cancer vaccine triggered antitumor immune responses in a tumor antigen-specific manner." (PMID 34439192, 2021). "Upon tumor challenge or IL-15 treatment, NK cell reduction was more profound in cKO mice, and IL-15-driven proliferation, survival, and activation were impaired in METTL3-deficient NK cells." (PMID 34535671, 2021). "IL-15 has an essential role in NK cell proliferation and survival and promotes NK cell anti-tumour effector function via stimulation of IFN-γ, granzyme B and perforin production." (PMID 34888493, 2021).
tumor (continued). "A subsequent study reported that the combination of cetuximab and IL-15 further activated tumor killing by NK cells and stimulated the maturation of dendritic cells (DCs) in a co-culture experiment with the TNBC cell line IIB-BR-G." (PMID 34207383, 2021). "Tumor volumes were significantly lower in IL-15-injected mice compared to that in the control mice, especially in the later stages." (PMID 33912464, 2021). "In CISH−/− mice, the resultant upregulation of IL-15 signalling mediated resistance to tumour metastasis in vivo." (PMID 34897554, 2021). "Systemic delivery of IL-15, a cytokine similar to IL-2, triggers proliferation of NK cells and enhances anti-tumor immunity of CD8 T cells in several preclinical animal model studies." (PMID 35127700, 2021). "Patients with poor OS who died during the follow-up period demonstrated considerably increased IL-15 values in contrast to the significantly low IL-15 levels in patients with a Grade 3 tumor and positive survival outcome." (PMID 32929618, 2021). "The author indicated that IL-15 production induced by anti-MARCO locally in the tumor and possibly the draining lymph node will support the proliferation, migration, and cytotoxic capacity of NK cells." (PMID 34177887, 2021). "Combinations with other immunotherapies are being investigated to improve the anti-tumor efficacy of IL-15 agents in the clinic." (PMID 33671252, 2021). "Multiple approaches focus on stimulating the 4-1BB and interleukin 15 (IL-15) pathways to activate and expand anti-tumor T cells or NK cells." (PMID 34244816, 2021). "By increasing the tumor expression of IL-15, the tumor acquired hot features with a raised infiltration of IFN+ T cells." (PMID 34150739, 2021). "Further analyses show that METTL3-mediated m6A methylation safeguards signaling pathways downstream of IL-15R, thereby regulating NK cell responsiveness to IL-15 in the tumor microenvironment (TME)." (PMID 34535671, 2021). "IL-15 reportedly improves in vivo anti-tumor activity of adoptively transferred CD8+ T cells and expands self-reactive CD8+ T cells." (PMID 33953717, 2021). "Correspondingly, a recent publication found that IL-15-expanded CD19-CAR-T cells demonstrated enhanced anti-tumor efficacy compared to those cultured with IL-15/IL-7." (PMID 34298748, 2021). "Collectively, the BV-based IL-15:IL-15Rα cell-based cancer vaccine induced potent antitumor responses in both the spleen and the circulatory system through a tumor antigen-specific CD8+ T cell-dependent mechanism." (PMID 34439192, 2021). "Tumor-infiltrating NK cells are activated by direct recognition of tumor cells or by pro-inflammatory cytokines, including IL-12, IL-15 and IL-18." (PMID 34203391, 2021). "For instance, the sustained persistence of IL-15 in the tumor microenvironment induced the expression of the IL-15-inducible inhibitor of IL-15-signalling, namely, cytokine-inducible SH2-containing protein (CISH)." (PMID 34203391, 2021). "The data collected implies statistically significant differences concerning IL-15 levels in patients with a Grade 3 tumor (G3) in respect to OS and DFS." (PMID 32929618, 2021). "Tumor cells treated with IL-15 show an expansion of NK cells and CD8-effector memory T-cells, killing cancer cells via stimulating the release of perforin and granzymes." (PMID 34725602, 2021). "For example, coadministration of IL-15 with tumor-directed monoclonal antibodies enhanced Ab-dependent cellular cytotoxicity by augmenting both NK cell and macrophage activation." (PMID 33156338, 2021). "These moDC, for monocyte-derived DC, can have the same presenting role as the resident cDC1 and produce high levels of IL-15 in order to support anti-tumor T helper cell type I responses or express TRAIL to mediate tumor cell apoptosis." (PMID 33418996, 2021). "The IL15-hUCBMSCs induced NK- and T-cell accumulation at the tumor site and established tumor-specific T-cell memory immunity." (PMID 33849537, 2021).
tumor (continued). "Both hetIL-15 and variants of IL-15:IL-15Rα complexes (N-803 and RLI) showed improved pharmacokinetics and anti-tumor activity in animal models and in humans." (PMID 33671252, 2021). "Like NK cells, ILC1s are dependent on IL-15 and exhibit potent cytotoxic activities against tumor cells, limiting tumor growth in mammary preclinical model." (PMID 33777750, 2021). "Recent preclinical studies in murine models have demonstrated that the combination of IL-15 and NKTs enhanced anti-tumor activity against NBL." (PMID 33668573, 2021). "Altogether, our study reports the importance of METTL3-mediated m6A methylation in regulating homeostasis and anti-tumor immunity of NK cells through retention of intact IL-15-dependent signaling pathways." (PMID 34535671, 2021). "We identified an inverse association between PD-L1 expression in tumour cells and the plasmatic level of VEGF and two T-helper 1 (TH1) cellular immunity-related cytokines, namely IL-15 and TNF-β." (PMID 33446741, 2021). "My results showed that IL-10 and IL-15 administration led to reduction in tumor volume and increase in survival." (PMID 33912464, 2021). "Tumor weights at day 22 of the mice immunized with IL-15:IL-15Rα-B16F10-OVA were smaller than those of the controls 3–3.5-fold." (PMID 34439192, 2021). "In our previous publication we also observed upregulated expression of NK cell perforin and NKG2D with IL-15, that increased in the presence of tumor cells." (PMID 33777767, 2021). "We previously demonstrated that EE exposure increases the accumulation of NK cells in the tumor mass with an IL-15-dependent mechanism." (PMID 34552593, 2021). "Compared to IL-2 conditioning, expanding T cells with IL-15 vastly improves mitochondrial fitness, prevents overt T cell differentiation and improves tumor immunity." (PMID 33815400, 2021). "The inability of cytotoxic T-lymphocytes to eliminate tumours that lack the expression of IL-15 and stress signals proposes a crucial role of IL-15 in immune responses." (PMID 33446741, 2021). "This unconventional cytotoxic subpopulation of CD56bright NK cells is reminiscent of the potent anti-tumor NK cells described after blood cell IL15 priming that result in enhanced elimination of multiple myeloma." (PMID 33708215, 2021). "For example, IL-15 produced within the tumour by an oncolytic vesicular stomatitis virus-induced greater anti-tumour compared to systemic IL-15 administration." (PMID 34888493, 2021). "The tumor weights from the mice treated with the IL-15:IL-15Rα-B16F10-OVA vaccine were a fifth of those from the control groups after 21 days of tumor implantation." (PMID 34439192, 2021). "In conclusion, for the first time, we presented the hIL15-ABD, the novel recombinant IL15 protein, was superior to in induction of tumor regression and antitumor immunity." (PMID 33918641, 2021). "More recently, fourth-generation CAR-T cells, also called “TRUCK” T cells, provided with stimulatory cytokines including IL-12, IL-15, IL-18 that antagonize the immunosuppressive tumor environment." (PMID 32083009, 2020). "While IL-15 has also shown promise as a monotherapy in a variety of tumor models by facilitating induction of CD8+ T cells and NK cells, its antitumor effect is synergistically enhanced when administered in combination with other cytokines, including IL-12." (PMID 33182232, 2020). "The continuous intra-tumoral expression of IL-15 enhanced T cells anti-tumor response and also reduced the tumor mass." (PMID 33117331, 2020). "These “armored” CAR-transduced NK cells constitutively produced transgenic soluble IL-15 that sustained their growth over a period of 42 days in culture and improved their anti-tumor capacity." (PMID 33371456, 2020). "The combination group showed significantly greater tumor reduction compared with IL-15 treatment or CD44-targeted NIR-PIT groups at 5, 7, and 10 days (p < 0.05, Tukey–Kramer test)." (PMID 32927646, 2020).
tumor (continued). "Examination of this tumor system was extended by evaluating TRAMP-C2 administered on each flank with anti-CD40 administered intratumorally in one flank tumor and IL-15 administered systemically." (PMID 32508818, 2020). "We demonstrated that the novel double-regulated OAd expressing IL-15 produced an enhanced anti-tumor effect against GBM cells." (PMID 33133514, 2020). "Preclinical studies on Sushi-IL15-Apo, a triple recombinant protein conjugated with polipoprotein A-I to bind to SR-BI on tumor cells, displayed improved ADCC activity against a tumor of this chimeric protein." (PMID 33266177, 2020). "Upon challenge, however, low levels of IL-15 were more protective and resulted in a greater production of anti-tumor cytokines such as IFN-γ and MIP-1β and a greater amount of CD11b+ and CD3e+ cells infiltrating tumors." (PMID 33096755, 2020). "The combination of IL-15 with tumor specific monoclonal antibodies has shown efficacy with a number of anticancer antibodies." (PMID 32508818, 2020). "The authors found that RANTES and IL-15 expressed from the oncolytic virus within the tumor was able to increase tumor infiltration by the CAR-T cells that were delivered systemically." (PMID 32604787, 2020). "In contrast, fresh negatively isolated Vδ2+ T cells did not exhibit suppressive behavior, even after stimulation with IL-12/IL-18/IL-15 or the sheer contact with BTN3A1-expressing tumor cells." (PMID 32456316, 2020). "The delivery of IL-15/IL15Rα (pAG208) protected more animals from developing a second tumor than the delivery of IL-15 alone (pAG170) or the delivery of both genes on separate plasmids (pAG115 and pAG170)." (PMID 33096755, 2020). "Our results would predict that shifts in STAT1 splicing towards a predominant expression of Stat1β would considerably compromise NK cell-dependent tumor surveillance and that this defect cannot be overcome by treatment with exogenous IL-15/IL-15Rα." (PMID 33042133, 2020). "In light of this, we investigated if the cytotoxic advantage of IL-2/IL-15-expanded Vγ9Vδ2 T cells was maintained in hypoxia, a state more representative of the tumor microenvironment in vivo." (PMID 32983105, 2020). "Simultaneous inhibition of two regulatory 7-cell inhibitory checkpoints enhanced IL-15 efficacy in murine tumor models." (PMID 32508818, 2020). "As a novel molecular agent, IL-15 is used in tumor research and shows powerful antitumor immune responses through the stimulation of natural killer cells." (PMID 32587256, 2020). "A recent upgrade to TriKEs is the replacement of the second tumor antigen-targeting scFv with IL15, as a way of increasing NK cell activation and expansion, simultaneously to promoting NK cell trafficking to tumors." (PMID 33120910, 2020). "CIS (encoded by the Cish gene in mice) is a checkpoint of NK cell activity in tumour immunity as it negatively regulates IL‐15 signalling in NK cells." (PMID 32745353, 2020). "Although it is well established that IL-15 or IL-15/IL-15Rα complex can be a potent stimulator of T cytotoxic and NK cells, high levels of IL-15 or the complex can actually result in reduced proliferation, exhaustion, and reduced anti-tumor activity." (PMID 33096755, 2020). "The histology of tumors collected during the course of treatment showed increased tumor damage when IL-15 was locally expressed compared to the controls." (PMID 33096755, 2020). "We did not observe differences in expansion rate or Vγ9Vδ2 T cell purity between the conditions; however, IL-2/IL-15-expanded Vγ9Vδ2 T cells displayed enhanced cytotoxicity against tumor cells, also in hypoxia." (PMID 32983105, 2020). "Briefly, the resected tumor specimen is divided into ~1–2 mm fragments and then cultures individually in a high concentration of IL-2 (and IL-15, IL-21 if necessary)." (PMID 32083009, 2020). "The expression of IL-15 from pAG208 and pAG170 is driven by different promoters and, as such, the expression levels detected in the tumor are different." (PMID 33096755, 2020).
tumor (continued). "Mouse CD8+ T cells cultured in the presence of IL-2 and IL-15 (the latter promotes T cell differentiation into memory phenotypes) show greater tumor cytotoxicity than cells cultured in the presence of IL-2 alone." (PMID 32221812, 2020). "Application of NDV vectors expressing IL-15 or IL-12 for intratumoral immunization of B16F10 melanoma tumor-bearing mice effectively suppressed tumor growth." (PMID 33218001, 2020). "For the sake of utilizing the enhanced anti-tumor capacity of IL-15, we inserted the IL-15 gene into the CMV promoter in the E3 region to control its expression." (PMID 33133514, 2020). "In this study, we sought to augment the effects of tumor targeted NIR-PIT using interleukin-15 (IL-15)." (PMID 32927646, 2020). "IL‐15 treatment triggered immune activation and promoted tumor depletion but also induced systemic inflammation, resulting in death of the treated mice." (PMID 32578942, 2020). "IL-15 has appeared as an important cytokine that increases the anti-tumor response of CD56bright NK cells." (PMID 33120910, 2020). "Longitudinal analysis of tumor progression showed the cam1615B7H3 treated mice displayed the lowest tumor progression, when compared to the IL-15 treated or tumor only mice." (PMID 32961861, 2020). "Using GET to deliver IL-15 and the soluble IL-15Rα on a single plasmid (pAG208), we were able to demonstrate an effective local anti-tumor response similar to that obtained using IL-15 only (pAG170)." (PMID 33096755, 2020). "The ineffectiveness of TIM-3 blockade in intra-tumor NK cells also reveals the role of tumor-specific factors, and its potentiation after activation with IL-15 suggests that inflammatory cues also have a role to play." (PMID 32117298, 2020). "NK cells pre-exposed to IL-12, IL-15 and IL-18 accumulate in the tumor tissue and retain their anti-tumor function both in vitro and in vivo." (PMID 32762681, 2020). "The isolated NK cells were firstly stimulated with cytokines (IL-15, IL-12 and IL-2) for 7 days and their cytotoxic function was then evaluated via a 6-h co-culture with a NK sensitive tumor cell line, K562." (PMID 33036556, 2020). "Further, the GFP gene region was replaced with the human IL-15 gene, and the virus was able to release IL-15, which acted synergistically to enhance anti-tumor effects through increased activation of immune cells." (PMID 33133514, 2020). "The result claimed that IL7 and IL21 were superior to IL2 and IL15 in enhancing tumor eradication, although IL2 and IL15 established increased effector functions." (PMID 33381115, 2020). "A recent study showed that CD19-CAR NK cells isolated from UCB transduced to express IL-15 and an iCaspase-9-based suicide gene had effective and persistent anti-tumor activity in NOD scid gamma (NSG) mice." (PMID 33287875, 2020). "From the results obtained in this study, it appears that the level of IL-15 expressed in the tumor has a greater impact on the overall survival and protection from challenge than the presence or absence of the soluble receptor." (PMID 33096755, 2020). "cam1615B7H3 induced NK cell expansion and cytolytic activity and led to reduced tumor burden in mice containing B7-H3 expressing ovarian carcinoma xenografts when compared to NK cells that only received infusions of IL-15." (PMID 33371456, 2020). "In this review, we discuss the distinct roles of IL-2 and IL-15 in activating various functions in T and NK cells with a particular focus on the signals that participate in the resistance of tumor-derived immune suppressive factors." (PMID 33266177, 2020). "On the other hand, in this study, the combination with IL-15 therapy was effective in all three tumor models including MOC1." (PMID 32927646, 2020). "In preclinical models, agonists of the stimulator of IFN genes (STING) pathway induce tumor regression by stimulating IL-15 production by infiltrating myeloid cells." (PMID 33584718, 2020).